BRD4 (bromodomain containing 4)
Diseases named in the same sentence as BRD4 in open-access papers (continued):
Sharing a sentence is not in itself a finding about the gene and the disease.
cancer (continued). "More recently, the discovery of the interaction of the coactivator bromodomain-containing protein (BRD4) with YAP-TAZ-TEAD1 to enhance the transcription of cancer related genes opened the way for new therapeutic strategies targeting BRD proteins to inhibit YAP activity in tumors." (PMID 31817001, 2019). "Brd4, like Gli2, is a target in developmental diseases and cancer, and Brd4 inhibitors may be useful in clinical settings in children." (PMID 31292434, 2019). "Given that the expression of Bcl-xl and Mcl-1 was stringently maintained by BRD4 in other cancer cells, we assumed that BETd-260 might also impact the expression of these two anti-apoptotic Bcl-2 family members in OS cells." (PMID 31653826, 2019). "Furthermore, in a total analysis of pan-cancer patients, BRD4 expression was positively correlated with poor OS and DFS." (PMID 30988278, 2019). "We identified enrichment of the H3K4me3 or H3K27ac peaks at upstream of BRD4 in cancer cells." (PMID 30988278, 2019). "In summary, BRD4 expression is negatively related to the survival of cancer patients, and targeting BRD4 may confer a clinical benefit in cancer patients." (PMID 30988278, 2019). "Currently, most proteins degraded are those related to cancer, particularly BRD4." (PMID 31500395, 2019). "These cPRC1/BRD4 co-targets are involved in cancer and focal adhesion pathways." (PMID 30139998, 2018). "This study demonstrates the oncogenic potential of BRD4 amplification in cancer and establishes BRD4-amplified HGSOC as a potential patient population that could benefit from BET inhibitors." (PMID 30036377, 2018). "In addition, among these proteins, several recent studies have revealed that BRD4 plays crucial roles in transcription programs induced by cancer." (PMID 29796168, 2018). "Therefore, further studies are needed to investigate the anti-cancer effects of its highly selective BRD4 inhibition in sunitinib-sensitive and -resistant ccRCC." (PMID 29796168, 2018). "Therefore, in this study, we aimed to investigate the anti-cancer efficiency of JQ1 in vitro and in vivo and to elucidate the molecular mechanisms underlying BRD4 inhibition in sunitinib-sensitive and -resistant ccRCC." (PMID 29796168, 2018). "Studies on the cancer field have described that BRD4 contributes to the recruitment of the positive transcription elongation factor b (P-TEFb) complex (heterodimer of CDK9 and cyclin T1, T2, or K) to the promoter region and activates RNA polymerase II-dependent (RNAPII) transcription." (PMID 30647531, 2018). "Altogether our findings suggest that UP-ALL13 cells may represent a more faithful model of transcriptionally addicted cancer cells and could be useful to gain mechanistic insights on the action of BRD4 inhibitors." (PMID 30304769, 2018). "However, recent evidence indicates that BRD4 relevance in cancer goes beyond its role in transcription regulation and identifies this protein as a keeper of genome stability." (PMID 30466442, 2018). "JQ1, a main inhibitor of BRD4, was demonstrated to play a part in anti-fibrosis in many tissues and organs, like liver, kidney, lung and heart, in addition to its well accepted effects in suppressing cancer proliferation, inflammation and bone destruction." (PMID 30062054, 2018). "The uprising evidence of the transversal centrality of BRD4 in many cancer supporting processes provides new interpretation for the cytotoxic activity of BETi and in particular envisages new and wide possibilities for the clinical employment of these drugs in cancer settings." (PMID 30466442, 2018). "This facet of BRD4/BET activity has not been explored in detail in cancer, but is likely to underlie at least some of the clinical activity of BET inhibitors, in particular in relation to aberrant NFκB signaling." (PMID 29415456, 2018). "Furthermore, there was a strong correlation (R = 0.83) between DNA copy-number and BRD4 mRNA expression, suggesting selective evolutionary pressure for BRD4 gain in cancer." (PMID 30036377, 2018).
cancer (continued). "BRD4 inhibitors preferentially suppress the transcription of cancer-promoting genes compared with housekeeping genes, thereby resulting in the potent cytotoxicity in cancer cells." (PMID 29724031, 2018). "Across all cancer types, OC had the highest frequency of BRD4 amplification." (PMID 28881656, 2017). "It is remarkable to note that, although its inhibition causes potent anti-proliferative effects in various leukemic sub-types, BRD4 is generally not mutated in cancer and normal hematopoietic cells show no sensitivity to this inhibitor." (PMID 29240787, 2017). "Despite being an important cancer drug target, the role of epigenetic reader Brd4 in cell differentiation and development remains unclear." (PMID 29263365, 2017). "Brd4 inhibitors are promising drug candidates for treating cancers and other diseases." (PMID 29263365, 2017). "Inhibition of BRD4 by JQ1 was shown to potently inhibit human cancer cell growth." (PMID 29228703, 2017). "Notably, MZ1-mediated degradation of BET proteins in cancer cell lines was shown to be preferential for Brd4 over paralogous proteins Brd2 and Brd3, with an observed selectivity window of >10-fold in protein degradation activity, or DC50, for Brd4." (PMID 29118097, 2017). "BRD4 knockdown, on the other hand, inhibited cancer cell growth, and decreased G1 phase cells." (PMID 29228703, 2017). "The discovery of new BRD4 inhibitors may provide reference for drug design and make a contribution to the treatment of cancer or other diseases." (PMID 28300771, 2017). "Although BRD4 has been reported as a potential therapeutic target for several cancers, its role in GC is still unknown." (PMID 28415703, 2017). "The epigenomic reader Brd4 is an important drug target for cancers." (PMID 29263365, 2017). "As for mechanism of the suppression of BRD4 by JQ1, it is generally agreed that JQ1 competitively bind to acetyl-lysine recognition pockets, displace BRD4 from chromatin, and reduce the expression of oncogenes, leading to cancer cell growth inhibition and apoptosis." (PMID 28545522, 2017). "Bromodomain 4 (BRD4) is an epigenetic regulator that, when inhibited, has anti-cancer effects." (PMID 26575167, 2016). "In addition, the well-known c-myc oncogene, which is overexpressed in various cancers, is directly activated by BRD4." (PMID 27006472, 2016). "Because both kinases and BRD4 are promising targets for cancer therapy, dual inhibitors may be an effective strategy to overcome cancer heterogeneity or resistance." (PMID 26954019, 2016). "In this study, we hypothesized that BRD4 inhibitors would act as anti-cancer agents in HCC via c-Myc suppression." (PMID 26575167, 2016). "Inhibitors that block the interaction of BRD4 with acetylated histones have been demonstrated to have antiproliferative effects due to the silencing of oncogenes that are dependent on super-enhancers to maintain their high levels of expression in cancer cells." (PMID 27604143, 2016). "BRD4 is enriched in large numbers of enhancer regions, and also in some large super-enhancer regions, and mediates expression of key transcription factors important for cancer development and progression." (PMID 27283767, 2016). "Recent studies have demonstrated that BRD4 binds preferentially to super enhancers (SEs), long stretches of enhancers that control the expression of ‘cell identity’ genes in normal cells and tumor‐specific oncogenes in cancer cells." (PMID 27169980, 2016). "Therefore, combinatorial therapies using NSD2 inhibitors together with MEK or BRD4 inhibitors are likely to be effective in fighting RAS-dependent cancers with NSD2 overexpression." (PMID 27604143, 2016). "Bromodomain Adjacent to Zinc finger domain 1B (BAZ1B), Bromodomain PHD finger Transcription Factor (BPTF), Bromodomain containing 4 (BRD4) and CHD4 are key components of various epigenetic complexes implicated in cancer growth, progression and/or metastasis formation." (PMID 27779108, 2016).
cancer (continued). "The effect of JQ1 on MSCs in our study, as well as on cancer cell lines in the other studies, are in line with the previous studies showing that BRD4 activates the transcription of CCND1 and CCND2, and that their expression is reduced in NIH3T3 cells after knockdown of BRD4." (PMID 26830473, 2016). "Because the i-CDK9-induced MYC expression and binding to P-TEFb compensate for P-TEFb's loss of activity, only simultaneously inhibiting CDK9 and MYC/BRD4 can efficiently induce growth arrest and apoptosis of cancer cells, suggesting the potential of a combinatorial treatment strategy." (PMID 26083714, 2015). "Notably, given the potential utility of BET domain inhibitors for the treatment of various cancers, these findings provide additional insight into the molecular mechanisms by which BRD4 functions in ERα-regulated gene transcription." (PMID 25788266, 2015). "Given a critical role of PDGFRα in caner growth and metastasis, our finding of BRD4 epigenetic control of PDGFRα may lend important insights for cancer research as well." (PMID 26870791, 2015). "Accumulating studies have revealed the critical roles of Brd4 in cancer development." (PMID 24592384, 2014). "Development of small molecules or other strategies to block the chromatin-binding of Brd4 or to induce the expression of HEXIM1 may provide novel therapeutic options against cancer." (PMID 24592384, 2014). "That the BRD4 protein is among the major Achilles' heels of incurable AML became known not because of a chance observation but by using a powerful new methodology for detecting molecular weaknesses that are cancer cell-specific." (PMID 23303309, 2013). "One of the key functions of BRD4 in cancer is to regulate c-Myc expression." (PMID 23918227, 2013). "In translational models of solid and hematologic malignancies, the cancer-specific antiproliferative activity of JQ1 has been mechanistically linked to addiction to the BRD4 proto-oncogene or oncogenic MYC (a BRD4 target gene)." (PMID 22901802, 2012). "MCV is the proven causative agent for MCC and it also globally infects healthy individuals; this study therefore identified the Brd4-MCV LT interaction as an important target for developing effective therapeutic strategies to cure MCV infection and associated cancers." (PMID 23144621, 2012). "Thus, PDID-targeting compounds offer a unique opportunity to block replication of cancer-associated high-risk HPV E2, but overdosing may prevent BRD4 from binding to its chromatin targets." (PMID 40149571, 2025). "However, BRD4 inhibition decreased intratumoral M-MDSCs in multiple cancer models." (PMID 40762981, 2025). "In addition, another major problem with BRD4 inhibitors is that drug resistance to BRD4 inhibitors often appears in various cancer types with different mechanisms of action, especially as BRD4 inhibitors are less effective in solid tumors than in hematological malignancies." (PMID 40078291, 2025). "Therefore, potential inhibitors selective for Brd4, also acting antiangiogenically, may be desirable in cancer therapy." (PMID 40650308, 2025). "Moreover, the dimer downregulates the expression of Bromodomain‐containing protein 4 (BRD4), GRB2‐associated‐binding protein 2 (GAB2), and Insulin receptor substrate 2 (IRS2) proteins, all of which play crucial roles in cancer cell sustainability and progression." (PMID 40285526, 2025). "BRD4 is critically involved in various cellular processes, including transcriptional elongation, DNA damage repair, cell cycle progression, cell proliferation, and apoptosis, making it a key target for therapeutic intervention in several cancers and inflammatory diseases." (PMID 39274873, 2024). "Thus, BRD4 inhibitors might be more valuable in combination with ferroptosis inducers in FSP1-dependent cancer cells." (PMID 38565708, 2024). "Therefore, BRD4 inhibitors are being regarded as promising therapeutic agents for cancer treatment." (PMID 38410799, 2024).
cancer (continued). "The capability of BRD4 to influence the transcription of key oncogenes, like MYC, through its association with super-enhancers—large clusters of transcriptional enhancers critical for maintaining cell identity and disease progression, notably in cancer underscores its therapeutic relevance." (PMID 39770515, 2024). "However, the functional targets of BRD4 vary in other types of cancer." (PMID 38169595, 2024). "Indeed, one study suggested that BRD4 may affect the development of cancer by inhibiting ferroptosis." (PMID 38565708, 2024). "dBET6 downregulates the expression of myelocytomatosis viral oncogene (Myc) in all cancer cell lines, has anti-tumor effects, and can also block cell resistance in most chronic myeloid leukemia lines, and is more effective than the first-generation BRD4-targeted drug dBET1." (PMID 36770884, 2023). "Furthermore, BRD4, a member of the bromodomain-contained protein family, is known to be involved in tumorigenesis via its binding to acetylated histones in several types of cancers." (PMID 37444447, 2023). "The differential response we present here between highly malignant human cancer cells and normal mouse cells suggests that targeting transcription and inducing readthrough transcription by BRD4 + TOP1 coinhibition may be particularly effective in transcriptionally addicted malignant cells." (PMID 37831776, 2023). "However, it remains unknown if transcription of GDF15 relies on BRD4 throughout different cancer cell types." (PMID 37495707, 2023). "Taken together, these data suggest the presence of a functional interaction between BRD4 and LOXL2, which may underlie future therapeutic interventions for cancer treatment, and which we therefore further investigated at the molecular, cellular, and tumor levels." (PMID 37937685, 2023). "Thus, targeting BRD4 has been well-studied as a potential therapeutic method for cancers." (PMID 37509171, 2023). "Therefore, BRD2, BRD3, and BRD4 may be biomarkers for some cancers, and the development of their inhibitors may be a potential strategy for cancer treatment." (PMID 36793283, 2023). "Therefore, a Brd4-selective inhibitor may be more preferable to the pan-BET inhibitors for cancer therapy." (PMID 37049806, 2023). "Consequently, it may be useful to target BRD4-related alteration sites or enzymes to prevent cancer and give treatment." (PMID 37509171, 2023). "Although we observed remarkable changes in immune cells due to the addition of BRD4 inhibitor, which were well correlated with its antitumor responses, the effects of BRD4 inhibitor in addition to local RT were possibly, at least in part, attributed to its direct effects on cancer cells." (PMID 37685868, 2023). "More importantly, the RUNX2 gene promoter has been shown to be under direct control of BRD4 during osteoblast differentiation as well as in cancer, suggesting that BRD4 may serve as a “master-regulator” of both inflammation and vascular calcification in parallel." (PMID 36275740, 2022). "Finally, TcoFBase also displays detailed information for each peak of BRD4, such as downstream target genes, downstream regulatory information and Pearson correlation coefficients between BRD4 and downstream target genes across TCGA cancers." (PMID 34718747, 2022). "In addition, BRD4 is hyperphosphorylated in cancer, and this hyperphosphorylation may be the general mechanism supporting its oncogenic activity." (PMID 35402244, 2022). "In addition, BETis can inhibit BRD4 in cancer cells and normal cells, which may have an adverse effect on the function of BRD4 in normal cells." (PMID 35402244, 2022). "Therefore, targeting BRD4-related modification sites or enzymes may be an effective strategy for cancer prevention and treatment." (PMID 35402244, 2022). "Therefore, the combination of targeted modification enzymes or inhibitors of related signaling pathways with BRD4 inhibitors to treat cancer may solve the current problems of poor single-drug toxicity and specificity." (PMID 35402244, 2022).